CES1 (carboxylesterase 1)
Diseases named in the same sentence as CES1 in open-access papers (continued):
Sharing a sentence is not in itself a finding about the gene and the disease.
melanoma (continued). "Therefore, the specific expression pattern of 2-AG-hydrolyzing enzymes suggests differential roles of CES1 and MAGL in different melanoma subtypes." (PMID 39934865, 2025). "We show that in the absence of MAGL, CES1 significantly contributes to the hydrolysis of 2-AG and other glycerol esters in the skin, inhibiting melanoma progression." (PMID 39934865, 2025). "Intriguingly, CES1 was identified as the only 2-AG-hydrolyzing enzyme in this melanoma tissue, as MAGL and ABHD6/12 were not expressed." (PMID 39934865, 2025). "Our study suggests that 2-AG degradation to arachidonate favors melanoma progression, either reflecting the carcinogenic role of ARA or that monoacylglycerols like 2-AG and/or other CES1 substrates may exert antitumor effects, indicating that CES1 could be a potential therapeutic target." (PMID 39934865, 2025). "However, to date, the role of CES1 in skin or melanoma progression has not been reported." (PMID 39934865, 2025). "Importantly, CES1 was not responsible for the significantly lower NAE levels in melanoma tissues." (PMID 39934865, 2025). "We found that certain aggressive and metastatic nodular-like melanomas with low NAEs but high 1-stearoyl-2-arachidonoyl-sn-glycerol (SAG), 2-AG, and ARA levels can progress without MAGL and upregulate CES1 to drive the hydrolysis of 2-AG, 2-oleoylglycerol (2-OG), and other glycerol esters." (PMID 39934865, 2025). "Likewise, the lower anandamide and overall NAEs levels observed in the melanoma was not changed by JZL184 treatment, indicating that the biosynthesis of NAEs via N-acyl phosphatidylethanolamine phospholipase D (NAPEPLD) rather than hydrolysis by CES1 could be involved." (PMID 39934865, 2025).
metabolic syndrome (3 papers, 2021 to 2025). A cluster of metabolic risk factors for CARDIOVASCULAR DISEASES and TYPE 2 DIABETES MELLITUS. "Due to active transport energy consumption and large consumption of carboxylesterase 1 in the liver, the liver’s ability to metabolize lipids is decreased, resulting in dyslipidemia." (PMID 39902928, 2025). "Furthermore, positive correlations were found between different markers of metabolic syndrome (MetS) and CES1 mRNA expression." (PMID 34234263, 2021).
arterial hypertension (2 papers, 2022). "We previously studied the effect of three genetic markers in the CES1 gene (rs2244613 and rs71647871 and the variant with a weak promoter, CES1A1c) on the pharmacokinetics of enalapril in patients with arterial hypertension." (PMID 36553492, 2022).
attention deficit-hyperactivity disorder (2 papers, 2019 to 2023). A disorder characterized by a marked pattern of inattention and/or hyperactivity-impulsivity that is inconsistent with developmental level and clearly interferes with functioning in at least two settings (e.g. at home and at school). "CES1 is the main enzyme involved in methylphenidate metabolism; a stimulant used for the treatment of attention-deficit/hyperactivity disorder." (PMID 36947541, 2023). "Interestingly, another gene, CES1, showing signal in our discovery samples (p = 7.99*10−3) and mega-analysis (p = 1.94*10−2), was found to be related to taste reduction in attention-deficit/hyperactivity disorder children who underwent methylphenidate treatment." (PMID 31118907, 2019).
breast carcinoma (2 papers, 2016 to 2017). "Indeed, CES1 silencing or ICMT overexpression increased RhoA activity and prompted strong changes in cytoskeletal organization in breast cancer cells." (PMID 28729673, 2017).
congestive heart failure (2 papers, 2016 to 2022). Failure of the heart to pump a sufficient amount of blood to meet the needs of the body tissues, resulting in tissue congestion and edema. "Accordingly, we examined the impact of CES1 variants on plasma angiotensin II (ATII)/angiotensin I (ATI) ratio in patients with congestive heart failure (CHF) that underwent ACEI dose titrations." (PMID 27662362, 2016).
Hepatic fibrosis (2 papers, 2016 to 2022). The presence of excessive fibrous connective tissue in the liver. "Among other genes, increased CD36 and CAV1 expression and decreased expression of CES1 in obese iPSCs could have been responsible for excess lipid accumulation, resulting in differential expression of genes associated with hepatic fibrosis, a key feature of non-alcoholic fatty liver disease (NAFLD)." (PMID 35915082, 2022).
hypertriglyceridemia (2 papers, 2020 to 2022). A laboratory test result indicating elevated triglyceride concentration in the blood. "Human carboxylesterase 1 (hCE1), a serine hydrolase distributed in liver and adipocytes, is highly associated with type 2 diabetes and hypertriglyceridemia." (PMID 33147723, 2020).
liver cancer (2 papers, 2023 to 2024). An epithelial or non-epithelial malignant neoplasm that arises from the liver. "In this study, we have demonstrated that CES1 was selectively expressed at various levels in different liver cancer samples and HCC cell lines." (PMID 36472914, 2023). "Although artificially transfected CES1 exerted antiproliferative effects in liver cancer cell lines, the bona fide role of CES1 in HCC per se has not yet been well characterized." (PMID 36472914, 2023). "Herein, we analyzed the levels of CES1 protein in an array of human liver cancer samples (n = 120) using immunofluorescence staining with the reported anti-CES1 antibody." (PMID 36472914, 2023). "Given that we confirmed that liver cancer cells express varied levels of CES1, we sought to determine the role of CES1 in HepG2 cells, a well-characterized hepatoblastoma cell line that expresses high levels of CES1." (PMID 36472914, 2023). "Importantly, when we treated SNU449 cells (another liver cancer cell line that does not contain endogenous CES1) with cisplatin, we found a responsive cell killing effect." (PMID 36472914, 2023).
liver cirrhosis (2 papers, 2024). "In contrast, LC-induced increases in intestinal transit rate and decreases in plasma-binding proteins and QPV obviously decreased the plasma exposure of CES1 substrates, which partly attenuated the increases in the plasma exposures of CES1 substrates caused by liver cirrhosis." (PMID 38399287, 2024).
lung carcinoma (2 papers, 2021 to 2025). "Kim and colleagues have found that human neural stem cells encoding CES1 and sTRAIL genes showed a significant anticancer effect on lung cancer brain metastases in the presence of CPT-11." (PMID 40839370, 2025). "This concordance between in vitro and in vivo findings further supports the therapeutic potential of CES1 and sTRAIL as effective agents against lung cancer." (PMID 40839370, 2025). "We found that both the CES1 and sTRAIL groups demonstrated great antitumor efficacy in lung cancer and lung cancer brain metastasis models." (PMID 40839370, 2025). "However, a significant reduction in tumor size was observed when CES1 and sTRAIL mRNAs were combined in both lung cancer and lung cancer brain metastasis models." (PMID 40839370, 2025). "In this study, we used WJ-MSCs as cellular vehicles to deliver CES1 and sTRAIL mRNAs using LNPs combined with CPT-11 to treat lung cancer and lung cancer brain metastases." (PMID 40839370, 2025). "In conclusion, we found that WJ-MSCs carrying CES1 and sTRAIL mRNAs with CPT-11 had significant antitumor effects in both lung cancer and lung cancer brain metastasis models by promoting apoptosis and inhibiting angiogenesis and tumor cell proliferation." (PMID 40839370, 2025). "Importantly, these in vivo results were consistent with our previous in vitro data, in which treatment with CES1 and sTRAIL mRNAs, particularly in combination with CPT-11, significantly reduced the viability of H460-Luc lung cancer cells." (PMID 40839370, 2025). "This study presents a nonviral, stem cell–based therapy for brain metastatic non–small cell lung cancer using WJ-MSCs expressing sTRAIL and CES1." (PMID 40839370, 2025).
non-alcoholic fatty liver disease (2 papers, 2021 to 2024). "We aimed to investigate whether CES1 CNVs was associated with susceptibility to non-alcoholic fatty liver disease (NAFLD) in a Chinese Han population." (PMID 34234263, 2021). "Vitamin E also improves lipid metabolism in mice with non-alcoholic fatty liver disease through the Nrf2/CES1 signaling pathway and improves liver function, lipid metabolism, and oxidative stress in rats with NAFLD induced by a high-fat, high-cholesterol diet (HFD)." (PMID 39479196, 2024).
non-Hodgkin lymphoma (2 papers, 2017 to 2020). Distinct from Hodgkin lymphoma both morphologically and biologically, non-Hodgkin lymphoma (NHL) is characterized by the absence of Reed-Sternberg cells, can occur at any age, and usually presents as a localized or generalized lymphadenopathy associated with fever and weight loss. "The increased frequency of deficient CES1 enzyme activity has also been reported in non-Hodgkin lymphoma and B-cell chronic lymphocytic leukemia." (PMID 32466188, 2020). "CES1 has been linked to the pathogenesis of non-Hodgkin’s lymphoma, possibly involving a mechanism by which the downregulation or deficiency in CES1 reduces the ability of macrophages to kill cancer cells." (PMID 28818099, 2017).
acute coronary syndrome (1 paper, 2017). Signs and symptoms related to acute ischemia of the myocardium secondary to coronary artery disease. "The effects of CES1 S75N (rs2307240,C>T) on clopidogrel response among 851 acute coronary syndrome patients who came from the north, central and south of China were studied." (PMID 28775293, 2017).
alcoholic cirrhosis (1 paper, 2024). "It was reported that the amount of CES1 protein in patients with hepatitis C cirrhosis was approximately 1.47-fold that of patients with alcoholic cirrhosis." (PMID 38399287, 2024).
alcoholic liver diseases (1 paper, 2016). A disorder caused by damage to the liver parenchyma due to alcohol consumption. "In the present study, we investigated whether CES1 played a role in the development of alcoholic liver disease (ALD) and methionine and choline-deficient (MCD) diet-induced liver injury." (PMID 27075303, 2016).
alcoholic steatohepatitis (1 paper, 2016). "Both hepatocyte nuclear factor 4α (HNF4α) and CES1 were markedly reduced in patients with alcoholic steatohepatitis." (PMID 27075303, 2016). "In the present study, we first investigated hepatic CES1 expression in patients with alcoholic steatohepatitis." (PMID 27075303, 2016). "To investigate whether CES1 is associated with the development of ALD, we investigated the expression of CES1 in patients with alcoholic steatohepatitis." (PMID 27075303, 2016). "Importantly, we also show that hepatic CES1 is markedly reduced in patients with alcoholic steatohepatitis." (PMID 27075303, 2016).
breast tumors (1 paper, 2021). "In addition, some of the DEPs identified in these signaling pathways were also differentially expressed between the male and female breast tumors, such as the ones encoded by CES1, CRYAB, NSF, PRKDC and SERPIND1 genes." (PMID 33656060, 2021).
celiac disease (1 paper, 2024). An autoimmune genetic disorder with an unknown pattern of inheritance that primarily affects the digestive tract. "In addition, the promoter regions of Carboxylesterase 1 (CES1), alpha-2-macroglobulin like 1 (A2ML1) and Solute Carrier Family 39 Member 5 (SLC39A5) were significantly hypermethylated in celiac disease." (PMID 38780872, 2024).
cholestasis (1 paper, 2021). Impairment of the bile flow caused by obstruction within the liver, or outside the liver in the bile duct system. "Cancer and/or non-alcoholicfatty liver disease-related cirrhosis showed larger deteriorationin levels of CYP3A4, 2C8, 2E1, 1A6, UGT2B4/7, CES1, FMO3/5, EPHX1,MGST1/3, BSEP, and OATP2B1 than the cholestasis set." (PMID 34428046, 2021).
Down syndrome (1 paper, 2022). "The carboxylesterase CES1 is involved in cocaine metabolism, and hypermethylation of the promoter has been reported in patients with Down’s syndrome." (PMID 35578268, 2022).
gastric cancer (1 paper, 2025). A primary or metastatic malignant neoplasm involving the stomach. "Study showed that overexpression of AFP in gastric cancer patients significantly inhibited the infiltration of CD8+T cell, could promote liver metastasis by regulating the PTEN/AKT1/SOX5/CES1 signaling axis." (PMID 40900791, 2025).
glioma (1 paper, 2020). A benign or malignant brain and spinal cord tumor that arises from glial cells (astrocytes, oligodendrocytes, ependymal cells). "Recurrent deletions in previously unknown glioma genes NT5C2, ADGRL2, and UIMC1 were observed whilst SUB1, CES1, and ITGA6 were frequently methylated in human LGGs; frequent CNVs in these genes were also present in human GBMs." (PMID 32727536, 2020).
graft versus host disease (1 paper, 2024). An immune system disorder that occurs after allogeneic hematopoietic stem cell transplant and is a reaction of donor immune cells against host tissues. "Conversely, pathways significantly negatively correlated with CES1 included allograft rejection, antigen processing presentation, DNA replication, graft-versus-host disease, cell cycle, cytosolic DNA sensing pathway, and proteasome synthesis." (PMID 39574476, 2024).
heart failure (1 paper, 2023). Inability of the heart to pump blood at an adequate rate to meet tissue metabolic requirements. "According to the Genecards resource CES1 has a demonstrated role in cardiac conduction and cardiac drug metabolism while IRX6 is a potential hub gene in the pathogenesis of heart failure." (PMID 37277858, 2023).
hepatocholangiocarcinoma (1 paper, 2023). "Quantitative analysis further indicated that the average levels of CES1 protein in HCC were significantly lower than those in normal livers and that the levels in hepatocholangiocarcinoma were even lower than those in HCC." (PMID 36472914, 2023).
Hypercholesterolemia (1 paper, 2025). An increased concentration of cholesterol in the blood. "Hypercholesterolemia and CES1 can promote CNS relapse in AML patients, particularly through CES1’s potential role in modulating immune infiltration within the TME." (PMID 40771823, 2025).
hypopharyngeal carcinoma (1 paper, 2024). Carcinoma, predominantly squamous cell, arising from the epithelial cells of the hypopharynx. "In laryngocarcinoma and hypopharyngeal carcinoma tissues, we found that CES1 is elevated in tumor tissues (p < 0.05, p < 0.01)." (PMID 39472448, 2024).
influenza (1 paper, 2017). An acute viral infection of the respiratory tract, occurring in isolated cases, in epidemics, or in pandemics; it is caused by serologically different strains of viruses (influenzaviruses) designated A, B, and C, has a 3-day incubation period, and usually lasts for 3 to 10 days. "Human carboxylesterase 1 (CES1) is a serine esterase that hydrolyses various exogenous and endogenous compounds including oseltamivir, a prodrug used to treat influenza." (PMID 28437488, 2017). "Many people may be exposed to oseltamivir during an influenza pandemic, and the c.662A>G SNP can be an important clinical biomarker if it significantly decreases CES1 enzyme function in humans, although the frequency of the c.662A>G SNP is relatively infrequent." (PMID 28437488, 2017).
injury (1 paper, 2016). Damage inflicted on the body as the direct or indirect result of an external force, with or without disruption of structural continuity. "We then investigated how alcohol downregulated hepatic CES1 expression and whether CES1 played a role in the development of ALD and non-alcoholic liver injury." (PMID 27075303, 2016).
macrosomia (1 paper, 2016). "The average methylation level of CES1 in chr16: 55866758–55867030 was significantly increased in the macrosomia group (P = 0.0006)." (PMID 27888796, 2016).
methamphetamine dependence (1 paper, 2025). A drug dependence that is a psychological dependency on the regular use of methamphetamine. "Notably, the observed hypomethylation of GABRB1, and KCNQ2, along with the hypermethylation of CES1 and USP7, may underlie the pathophysiology of methamphetamine dependence." (PMID 41368944, 2025).
neuroblastoma (1 paper, 2022). Neuroblastoma (NB) is the most common solid, extracranial childhood tumor. "To assess the potential role of epigenetic control of CES1 promoter in neural cells as well, we used the neuroblastoma cell line SHSY5Y, which we treated with the DNA methyltransferase inhibitor 5-aza-2′-deoxycytidine (Aza)." (PMID 35578268, 2022).
preeclampsia (1 paper, 2021). Preeclampsia is a hypertensive disorder of pregnancy that is characterized by new-onset hypertension with proteinuria presenting after 20 weeks of gestation, and depending on mild or severe forms may initially present with severe headache, visual disturbances, and hyperreflexia. "The most relevant targets for preeclampsia were: AR, VDR, SLC6A2, NOS3 and CHRM4, while ABCG2, ERBB2, CES1 and REN led to the most relevant off-targets." (PMID 33546161, 2021).
prostatic intraepithelial neoplasia (1 paper, 2021). "IHC and HE staining assays were performed and demonstrated that loss of CES1 induced the higher ratio of prostatic intraepithelial neoplasia (PIN) in the anterior prostates, suggesting that the absence of CES1 mediated the transformation of normal prostate tissue into tumorous tissues." (PMID 34185414, 2021).
type 1 diabetes (1 paper, 2014). "Therefore, we also investigated the expression of CES1 in a type 1 diabetes mouse model." (PMID 25285996, 2014).
viral infections (1 paper, 2025). "BAY-M2d induced multiple antiviral genes (TLR7, CD74, CES1, HLA-DOA, CD209, and CMPL2), the products of which may be involved in resistance to viral infections." (PMID 40129989, 2025).